MTOR (mechanistic target of rapamycin kinase)
Diseases named in the same sentence as MTOR in open-access papers (continued):
Sharing a sentence is not in itself a finding about the gene and the disease.
cancer (continued). "PLAU has been observed to be associated with the Akt/mTOR/S6k pathway, which also activates cancer cell proliferation and migration." (PMID 39149564, 2024). "The activation of the mTOR signaling pathway is the key to the promotion of cell growth, and its abnormal expression is often associated with several cancers 49-51." (PMID 39668819, 2024). "Dysregulation of mTOR signaling is associated with human diseases including cancer, diabetes, aging, and mTORopathies." (PMID 38824577, 2024). "Elevated STAT3 activity induces resistance in PTEN-deficient cancer cells to PI3K/AKT/mTOR inhibitors." (PMID 39309860, 2024). "Dysregulation of mTOR signaling contributes to numerous diseases, whereby the continuous activation of mTOR has been implicated in many cancers due to uncontrolled cell proliferation and growth." (PMID 39770519, 2024). "Changes in the expression and activity of cancer-critical genes frequently cause mTOR signaling hyperactivation." (PMID 38539200, 2024). "Amongst them, 33 (25.2%) have been reported as GBM-related (e.g., EGFR, PTEN, MTOR) and 29 (22.1%) as cancer-associated genes (e.g., AGAP2, SOX2)." (PMID 38724522, 2024). "In contrast with CNIs, mTOR-Is decrease the risk of cancer and increase the survival rate of patients in the future." (PMID 39533221, 2024). "In this context, mTOR dysregulation is associated with various cancers, making this a significant finding." (PMID 39766256, 2024). "Among a variety of signaling pathways associated with the CSCs, PI3K/AKT/mTOR axis is deeply involved in cascades such as anti-oxidative mechanisms and anti-quiescence signaling, resulting in cancer resistance and survival in the end." (PMID 39349424, 2024). "The overexpression of the mammalian target of rapamycin (mTOR), a kinase that regulates cell growth and metabolism, in cancer, is associated with tumor progression, cancer drug resistance, and a worse prognosis." (PMID 38891882, 2024). "Further, autophagy induced by inhibiting the PI3K/Akt/mTOR pathway causes growth inhibition and death of cancer cells." (PMID 36923938, 2023). "The SMYD3 interactor mTOR is involved in the “avoiding immune destruction” cancer hallmark, and its signaling is a key regulator of immune cell metabolism and function." (PMID 37998381, 2023). "Recent studies have demonstrated that the mTOR pathway participates in the progression of cancer and other diseases associated with S100 protein dysregulation." (PMID 36835331, 2023). "One of the characteristic mutations that is found in many cancer types is associated with the mammalian target of rapamycin, i.e., mTOR." (PMID 37443747, 2023). "In many types of cancer, mutations activate mTOR, which is a critical controller of metabolic homeostasis." (PMID 37368660, 2023). "A recent study demonstrated a significant correlation between STAT3 and mTOR overexpression, which underlies cancer-mediated drug resistance and cancer progression." (PMID 37446140, 2023). "The overexpression of PI3K/AKT/mTOR signaling, which is linked to the regulation of distinct oncogenic mechanisms, has been reported in various forms of cancers, especially in colorectal cancers (CRC)." (PMID 36982677, 2023). "Dysregulation of mTOR has been implicated in many diseases, including cancer, metabolic diseases, neurological disorders and inflammation." (PMID 36994237, 2023). "Akt/mTOR pathway affects protein translation, survival, metabolism, its abnormalities can cause cancer." (PMID 36849137, 2023). "mTOR signalling pathways are considered the hallmark in cancer due to their dysregulation in approximately 70% of cancers." (PMID 37513916, 2023). "Numerous studies have found that mTOR is associated with a number of human diseases, such as cancers, neurodegenerative diseases and aging." (PMID 36873929, 2023). "The activation of mTOR in cancers can occur through the loss of PTEN function or increased AKT expression." (PMID 37240915, 2023).
cancer (continued). "The phosphatidylinositol (PI)-3-kinase (PI3K)/Akt/mTOR signaling pathway is associated with cancer progression, angiogenesis, chemotaxis and invasiveness." (PMID 37237486, 2023). "Activation of the Akt/mTOR pathway in cancer cells has been implicated in various aspects of tumorigenesis." (PMID 37571343, 2023). "Abnormal activity of mTOR is closely associated with the occurrence, development, metastasis, and drug resistance of various malignant tumors, including lung cancer." (PMID 36647780, 2023). "Loss of PTEN function can contribute to the development of cancer by activating PI3K/AKT/mTOR signaling." (PMID 37932340, 2023). "In certain cancer types, such as those with loss‐of‐function mutations in mTOR genes like TSC1, TSC2 or STK11, mTOR inhibitors have shown sensitivity." (PMID 38041544, 2023). "As an example, the mitochondrial nuclease ENDOG suppresses the mTOR pathway to promote autophagy, a conserved pathway for which impairment is also related to cancer (see ‘Hallmark 3: resisting cell death’ section)." (PMID 37278614, 2023). "PI3K/AKT/mTOR oncogenic signaling pathways often induce cancer progression and are associated with resistance to targeted anticancer therapies, and more research is still needed on the effectiveness of related inhibitors." (PMID 37641116, 2023). "Taken together, the results demonstrate that ATOH1 loss promotes cancer stemness through the ATOH1/GAS1/RET/AKT/mTOR signaling pathway in GAC, thus providing a potential therapeutic strategy for AKT/mTOR inhibitors in GAC patients with ATOH1 deficiency." (PMID 37824217, 2023). "In summary, the PI3K/AKT/mTOR pathway performs a significant function in tumour formation and is closely associated with the onset and advancement of malignant tumours." (PMID 36631680, 2023). "Cancer cells with a subset of mTOR-activating mutations are hypersensitive to the mTOR inhibitor rapamycin." (PMID 37445831, 2023). "As these outcomes are all associated with mTOR signalling, cell cycle and autophagy, we now provide a likely triggering mechanism for the anti‐cancer activity of monepantel." (PMID 37148543, 2023). "Its actions are mediated through inhibition of the mTOR protein kinase and associated with anti-proliferative and anti-cancer activity." (PMID 37236967, 2023). "The PI3K/Akt/mTOR pathway plays an important role in the regulation of cell proliferation and survival, and dysregulated PI3K/Akt/mTOR pathway is a hallmark of a variety of cancers." (PMID 37480137, 2023). "mTOR inhibitors are now part of oncologists’ armamentarium for various types of cancers, but patients who use these drugs are at a high risk of developing painful mouth sores." (PMID 38201496, 2023). "The loss of PTEN function activates the PI3K/AKT/mTOR pathway and results in the growth, proliferation, and survival of cancer cells." (PMID 37533462, 2023). "Previous studies have demonstrated a correlation between AKT/mTOR and the susceptibility of cancer cells to radiation." (PMID 37940975, 2023). "The blocking of PD-L1 can inhibit the glycolysis of cancer cells by inhibiting the activity of mTOR, thereby relieving the pressure of glucose deficiency in the tumor microenvironment and allowing the glycolysis and IFN-γ production of infiltrated T cells." (PMID 37434177, 2023). "Hanahan and Weinberg described that activation of mTOR signalling is the hallmark of a large number of cancers." (PMID 37513916, 2023). "In this regard, mTOR and mTOR-associated pathways are among the potential factors and pathways that are affected by lncRNAs in most cancers, especially CRC." (PMID 37280524, 2023).
cancer (continued). "In this scenario, PKC acts as a driving factor, and PLD is a crucial regulator of PKC-dependent mTOR activation; as a result, cancer cells become more susceptible to PLD and mTOR inhibitors." (PMID 37370855, 2023). "The PI3K/AKT/mTOR pathway in cell cycle regulation is one of the cellular signaling pathways widely known and reported to be associated with cancer." (PMID 38188676, 2023). "In general, the PI3K/AKT/mTOR pathway plays a critical role in the development and progression of cancer, and its abnormal activation is closely associated with cancer cell survival, proliferation, apoptosis, and resistance to drugs." (PMID 37998733, 2023). "The mammalian target of rapamycin (mTOR) kinase is a highly conserved regulator of survival signals, and its activation in the progression of cancer has been implicated in the control of PD-L1 expression." (PMID 37834467, 2023). "Each relapse AML sample showed over-representation of over- and under-expressed DEGs in TFs, drug-resistance genes, cancer-mutated genes (oncogenes and TSGs) and several cancer-related pathways (mTOR, MAPK, ErbB, FoxO, TNF and HIF-1 signaling, apoptosis)." (PMID 37031307, 2023). "GSVA/hallmark pathway analysis revealed significant upregulation of wnt β-catenin signaling, TGF-β signaling and PI3K/Akt mTOR signaling in cluster 1, implicating a variety of cancer-associated pathways were activated." (PMID 37151879, 2023). "According to the tumor genome sequencing datasets, thirty-three mTOR mutations involved in cancer have been identified." (PMID 37046703, 2023). "It has also been reported that FKBP12 bound to RapaLink-1 enhances the accumulation of Rapalink-1 molecules inside the cell, and thus makes it a potential drug to inhibit cancer-associated activating mTOR mutant." (PMID 37513916, 2023). "Numerous diseases, including ocular disorders, cancer, diabetes, and neurodegenerative diseases, have been linked to the activation of the mTOR signaling pathway." (PMID 37958901, 2023). "mTOR signalling is implicated in various diseases, like cancer, arthritis, insulin resistance, and osteoporosis and in tumour angiogenesis." (PMID 37513916, 2023). "The mammalian target of rapamycin (mTOR) is involved with malignancy-associated genes, which can promote cancer cell proliferation and inhibit apoptosis." (PMID 37894909, 2023). "The buildup of BCAAs in these cancer cells is associated with the promotion of tumor growth via the activation of mTORC1 and the mTOR downstream signaling pathway." (PMID 37755304, 2023). "The PI3K/AKT/mTOR signaling pathways have been known to be implicated in tumorigenic roles in various cancers via the EMT process." (PMID 36910848, 2023). "Due to the modulatory effects of lncRNAs in the dynamic growth of CRC via controlling mTOR and mTOR-associated pathways, it is highly recommended that the modulatory role of lncRNAs can be examined in other cancer types as well." (PMID 37280524, 2023). "Upregulation of the mTOR pathway is seen in most cancers and, in the case of HCC, associated with earlier recurrence and poor prognosis." (PMID 37131258, 2023). "PI3K/AKT/mTOR signaling is associated with the enhanced proliferation and growth of cancer cells, and its activation was strongly correlated with unfavorable survival and resistance to radiotherapy." (PMID 37802999, 2023). "Dysfunction of PIKK members and aberrant stimulation of the PI3K/AKT/mTOR signalling pathway are linked to a plethora of diseases including cancer." (PMID 37489050, 2023). "The molecular function analysis suggested that the signature was significantly correlated with cancer-associated pathways, including angiogenesis, epithelial mesenchymal transition, mTOR signaling, myc-targets." (PMID 38093298, 2023). "mTOR pathway is a major regulator of cell growth and division, and activating mutations have been reported in many different cancer types, including TC." (PMID 36969070, 2023).
cancer (continued). "High LAT1 expression in several cancers is associated with mTOR activation and resistance to chemotherapy." (PMID 36768934, 2023). "Hyperactivation of mTOR kinase by mutations in the PI3K/mTORpathwayor by crosstalk with other mutant cancer drivers, such as RAS, isa feature of many tumors." (PMID 36533617, 2023). "It has been reported that mTOR signaling is associated with cancer-cell resistance to microtubule-targeting agents, and the everolimus treatment effectively inhibits the mTOR-associated resistance." (PMID 38203186, 2023). "The mTOR protein has been reported to be activated by increased amino acid uptake, and is associated with chemoresistance in several cancers." (PMID 36768934, 2023). "They regulate the mTOR signaling pathway which has been found to be strongly linked to cancer in recent years." (PMID 37047148, 2023). "The hyperactivation of the PI3K/Akt/mTOR pathway is associated with drug resistance and cancer progression." (PMID 38203418, 2023). "Results showed that high-risk score patients were associated with cancer regulating related pathways, such as mTOR signaling pathway, WNT signaling pathway, and VEGF signaling pathway, etc.." (PMID 37014321, 2023). "Various cancers have been found to have mutated mTOR overexpression and some mTOR kinase signaling targets." (PMID 36597205, 2023). "The abortive PS exposure caused by DN-ANXA7J was concordant with the increase in mTOR in cancer cells." (PMID 37240163, 2023). "Overactivation of the PI3K/Akt/mTOR pathway has frequently been observed to be associated with proliferation and anti-apoptotic properties in a range of different cancers." (PMID 37584712, 2023). "Curcumin and plumbagin are promising anticancer drug candidates that potentially suppress the PI3K/Akt/mTOR pathway that causes cancer cell death." (PMID 37047624, 2023). "mTOR dysregulation is associated with cancer, and neurological, cardiovascular, and renal disorders, making it an excellent therapeutic target." (PMID 36766800, 2023). "Persistent CerS4 overexpression in MCF-7 cells activated multiple cancer-associated pathways, including pathways involving sterol regulatory element–binding protein, nuclear factor kappa B (NF-κB), Akt/mammalian target of rapamycin (mTOR), and β-catenin." (PMID 37885013, 2023). "The overactivation of mTOR is also associated with the development of various cancers, thus creating an opportunity to target this pathway with metformin and other therapeutic agents." (PMID 37760509, 2023). "Cancer genome analyses have found that many cancers have mutations affecting the PI3K/Akt/mTOR signaling pathway." (PMID 36986560, 2023). "In the last two decades, we have learned that each type of vascular malformation harbors inherited germline and somatic mutations in two well-known cellular pathways that are also implicated in cancer biology: the PI3K/AKT/mTOR and RAS/RAF/MEK pathways." (PMID 36846125, 2023). "The mutations of key regulators in the mTOR pathway significantly affect the survival and prognosis of cancer patients." (PMID 37263709, 2023). "One such pathway is the phosphoinositide 3-kinase (PI3K)/Akt/mammalian target of rapamycin (mTOR) signaling pathway, which is associated with poor prognosis in many cancer types." (PMID 37900167, 2023). "Studies have found that aberrant regulation of mTOR is a hallmark of many cancers and mTOR can be used as a therapeutic target for cancer." (PMID 37228652, 2023). "In several human cancers, the mutations in the mTOR gene that confer constitutive activation of mTOR signaling have been identified." (PMID 37446128, 2023).
cancer (continued). "Previous studies on the mechanism‐of‐action of monepantel have predominantly pointed to autophagy, mTOR signaling and the cell cycle as critical pathways associated with the anti‐cancer effects of the drug, though apoptosis has also been implicated." (PMID 37148543, 2023). "Overall, the disruption of PI3K/AKT/mTOR signaling has been implicated in cancer, immunological disorders, diabetes, and cardiovascular disease, and led to the development of therapies targeted at PI3K pathways." (PMID 36986560, 2023). "mTOR signaling has been associated with accelerated aging, and dysregulation of mTOR signaling has also been connected to the advancement of cancer, inflammatory and neurological illnesses, as well as T2DM." (PMID 38139841, 2023). "During cancer pathogenesis for example, the extent of interplay between ERK1/2 and mTOR signaling pathways is associated with cancer progression and metastasis." (PMID 37161542, 2023). "Current studies have shown that aberrant mutations in the PI3K/AKT/mTOR signalling pathway are closely related to the development and prognosis of cancer." (PMID 35165269, 2022). "Dysregulation of mTOR signaling is implicated in a number of common human diseases, including cancer, metabolic syndrome, cardiovascular diseases, and neurological and psychiatric disorders." (PMID 36045116, 2022). "In this context, it should be stressed that the PIK3/AKT/mTOR signaling cascade is strictly associated with BC, and many of the genes encoding for elements of this pathway are mutated in this cancer type." (PMID 35628294, 2022). "Malonylcarnitine is a precursor of Malonyl‐CoA that causes malonylation of mTOR by its increase, and thus has a positive effect on the angiogenesis and the pathogenesis of cancer." (PMID 35284957, 2022). "On the contrary, in m7Gcluster B, various oncogenic signaling pathways such as mTOR, Notch and cancer associated pathways were strikingly suppressed, and immune activation process were significantly activated." (PMID 36246663, 2022). "Cancers that acquire a mutation/copy gain in PIK3CA or loss of PTEN have been implicated in enhanced sensitivity to inhibitors targeting the PI3K/AKT/mTOR pathway." (PMID 35918763, 2022). "In reaction to a variety of intracellular and extracellular signals, together with glucose, cytokines, amino acids, and PAMPs (pathogen-associated molecular patterns), mTOR displays critical role in development, cellular proliferation, immunology, and cancer." (PMID 36293326, 2022). "The relationship between mTOR gene variants rs2295080 T/G and rs1883965 G/A and the risk of cancer remains inconsistent." (PMID 35082928, 2022). "Gain-of-function mutations affecting the Ras/BRAF/MEK/ERK1/2 and PI3KCA/AKT/mTOR pathways have been identified in many types of cancer and VAs." (PMID 35574555, 2022). "MTOR, as an important regulator of autophagy, has been reported to associate with various pathologies such as cancer and cardiovascular diseases." (PMID 35397636, 2022). "Tumor gene activation mutations (such as PIK3CA, AKT, and mTOR) are closely related to cancer growth and therapeutic drug resistance." (PMID 36452344, 2022). "For example, loss‐of‐function mutations in tumor suppressor proteins such as LKB1 (AMPK signaling pathway) and TSC (mTOR signaling pathway) are associated with the pathogenesis of various types of cancer." (PMID 35347892, 2022). "A variety of signaling pathways including TNF-α, KRAS, IL-6/JAK/STAT3, IL-2/STAT5, epithelial-mesenchymal transition, oxidative phosphorylation, and mTOR were found to be significantly associated with TRPs in pan-cancer." (PMID 35831825, 2022).